TTTY6B (testis expressed transcript, Y-linked 6B)
Synonyms: LINC00128
Gene: Long non-coding RNA gene on chromosome Y (22,131,944 to 22,146,831, forward strand). Ensembl gene ENSG00000131548.
Homologues: Paralogues in human: TTTY6 (100% identical).